IGFBP7 (insulin like growth factor binding protein 7)
Diseases named in the same sentence as IGFBP7 in open-access papers (continued):
Sharing a sentence is not in itself a finding about the gene and the disease.
colorectal cancer (continued). "This conclusion also pertains to the expression of IGFBP7 in prostate and colorectal cancer." (PMID 32500027, 2020). "Similarly, elevated IGFBP7 expression was detected in specific stages of colorectal cancer and silencing of IGFBP7 reduced proliferation as well as colony formation in colorectal cancer cell lines." (PMID 25887188, 2015). "IGFBP7 intragenic mutations were also not found in relation to down-regulation in breast and colorectal cancers, although there is evidence of epigenetic silencing occurring in other types of cancer cell lines." (PMID 25886299, 2015). "It has become increasingly apparent that the levels of IGFBP7 differ in different cancer types, where relatively higher levels of expression have been described in gliobastomas multiforme, oesophageal squamous cell, and colorectal carcinoma." (PMID 25886299, 2015). "Downregulation of HSP60 may be responsible for, at least in part, the proliferation inhibiting role of IGFBP7 in colorectal cancer cells." (PMID 20433702, 2010). "CIMP-specific inactivation of BRAFV600E-induced senescence and apoptosis pathway by IGFBP7 DNA hypermethylation might create a favorable context for the acquisition of BRAFV600E in CIMP+ colorectal cancer." (PMID 20027224, 2009). "CIMP-specific inactivation of BRAFV600E-induced senescence and apoptosis pathways by IGFBP7 DNA hypermethylation might create a favorable context for the acquisition of BRAFV600E in CIMP+ colorectal cancer." (PMID 20027224, 2009). "Interestingly, inhibition of HSP60 could enhance the tumor suppressive activity of insulin-like growth factor binding protein 7 (IGFBP7) in colorectal cancer cells." (PMID 32351972, 2020). "Similar results were observed in colorectal cancer where serum and tumor-specific IGFBP7 levels were not correlated." (PMID 34606580, 2021). "Initial studies have suggested that IGFBP7 expression is drastically up-regulated in colorectal cancer (CRC) tissues compared with their paired non-cancerous tissues." (PMID 32500027, 2020). "The inactivation of a senescence pathway by IGFBP7 DNA hypermethylation in CIMP+ tumors may provide a permissive environment for the acquisition of BRAFV600E, thus providing a possible explanation for the link between BRAFV600E and CIMP in colorectal cancer." (PMID 20027224, 2009). "Real-time RT-PCR analysis of colorectal cancer cell lines showed that IGFBP7 mRNA expression was inversely related to DNA hypermethylation, as cell lines with IGFBP7 hypermethylation showed little or no IGFBP7 gene expression." (PMID 20027224, 2009).
Insulin resistance (24 papers, 2008 to 2025). Increased resistance towards insulin, that is, diminished effectiveness of insulin in reducing blood glucose levels. "IGFBP-7 is proven to be associated with insulin resistance (IR) and the development of metabolic syndrome (MetS)." (PMID 35625639, 2022). "An increased concentration of IGFBP7 is also associated with insulin resistance (IR) and the risk of metabolic syndrome (MetS)." (PMID 35204773, 2022). "The association between IGFBP7 and type 2 diabetes was reported in two cross-sectional studies that indicated the positive correlation of serum IGFBP7 levels with insulin resistance and endothelium-dependent vasodilation." (PMID 26974954, 2016). "The high synthesis of IGFBP-7 overexpression is associated with insulin resistance; TGF-β is responsible for the initiation of fibrotic processes; MMPs and TIMPs are associated with cardiac remodeling; and miRNAs control diverse pathways in the pathogenesis of DCM." (PMID 39335666, 2024). "Serum IGFBP-7 levels are associated with insulin resistance and the risk of metabolic syndrome." (PMID 27769173, 2016). "Data in their study implicated that IGFBP-7 was associated with insulin resistance." (PMID 24180466, 2013). "Previous studies have suggested that serum IGFBP-7 levels may be associated with insulin resistance in type 2 diabetes (T2D)." (PMID 24180466, 2013). "Nevertheless, we have a hypothesis that low IGFBP-7 levels may be related to increased insulin and consequently associated to insulin resistance." (PMID 24180466, 2013). "Functionally, IGFBP7 contributes to fibrogenesis by playing a role in the activation and transdifferentiation of hepatic stellate cells, and knockdown of IGFBP7 in mouse models of MASLD resulted in reduced insulin resistance and hepatic steatosis." (PMID 40552595, 2025). "Knockdown of IGFBP7 in a mouse model of MASLD resulted in a reduction of insulin resistance and hepatic steatosis." (PMID 38811591, 2024). "On the other hand, IGF binding protein 7 (IGFBP7), also known as IGFBP-related protein 1, is thought to be associated with the presence of insulin resistance and correlates closely with the degree of steatosis and fibrosis in patients with NAFLD." (PMID 38709454, 2024). "Subsequently, IGFBP7 induces hepatocyte insulin resistance, hyperlipidemia, and hyperglycemia prior to the production of KC-derived pro-inflammatory cytokines." (PMID 33659253, 2021). "We then analyzed the correlations between serum IGFBP-7 protein levels and other laboratory variables, including fasting glucose, fasting insulin, homeostasis model of assessment insulin resistance (HOMA-IR), IGF-1, and IGFBP-1." (PMID 24180466, 2013). "Low serum IGFBP-7 levels are related to low IGFBP-1 and subsequently associated with insulin resistance in T2D." (PMID 24180466, 2013). "It has been suggested that IGFBP7 may negatively affect the regulation of hepatic glucose and lipid metabolism secondary to insulin resistance due to its ability to bind directly to insulin receptors." (PMID 38709454, 2024). "Insulin resistance is associated with increased circulating levels of IGFBP7 in non-diabetic men14 and the IGFBP7 gene in whole blood samples displays differential DNA-methylation in men recently diagnosed with type 2 diabetes." (PMID 39280605, 2024). "We noted that IGFBP7 was up-regulated while IRS-3 was down-regulated and involved in insulin signaling pathway, implying that IGFBP7 may induce insulin resistance by inhibiting IRS-3." (PMID 31805951, 2019). "IGFBP7 binds to insulin and thereafter inhibits the binding of insulin to IR, impairing the subsequent signaling, which at least in part leads to the pathological state of insulin resistance and hyperinsulinemia." (PMID 27101796, 2016). "The correlation between IGFBP-7 and IGFBP-1 suggests that low IGFBP-7 may be associated with insulin resistance in T2D." (PMID 24180466, 2013).
Insulin resistance (continued). "Recently, more attention has been drawn to the effects of insulin-like growth-factor-binding protein 7 (IGFBP7) as a marker of cellular senescence, insulin resistance and atherosclerosis." (PMID 35204773, 2022). "One of them may be the insulin-like growth factor binding protein 7 (IGFBP7)—a novel marker of cellular senescence, insulin resistance, and atherosclerosis." (PMID 35625639, 2022). "However, owing to its solid binding affinity to insulin (unlike IGFBP 1–6), IGFBP7 can influence insulin’s physiological activity, possibly contributing to insulin resistance, facilitating the progression of diabetes, as demonstrated by several studies." (PMID 39335666, 2024). "Interestingly, variations in the IGFBP7 isoform appeared to differentially bind the insulin receptor, possibly explaining why some obese patients develop insulin resistance whereas others do not." (PMID 34025667, 2021). "Furthermore, liver macrophages contribute to insulin resistance independently of their inflammatory status, through the secretion of IGFBP7, a non-inflammatory factor with a high capacity to bind the insulin receptor and induce lipogenesis and gluconeogenesis through the activation of ERK signaling." (PMID 32526449, 2020). "However, since insulin resistance is also evident in non-diabetic dialysis patients, the increase in serum IGFBP7 levels might also be due to insulin resistance." (PMID 19019211, 2008).
glioblastoma (20 papers, 2009 to 2024). The most malignant astrocytic tumor (WHO grade IV). "Increased IGFBP7 levels were found in CNS pathological conditions, such as glioblastoma and stroke, as well as EAE in a previous study." (PMID 34489947, 2021). "We have previously demonstrated that TGF-β induces the expression and secretion of IGFBP7 in U87MG glioblastoma cells." (PMID 34356861, 2021). "Increased IGFBP7 expression in vasculature was observed in brain pathological conditions including glioblastoma and stroke, as well as other types of tumors." (PMID 33505428, 2020). "Igfbp7/IGFBP7 expression was up-regulated in all these disease models as well as glioblastoma vasculature, suggesting that its up-regulation is a universal response in EC to pathological alterations rather than TBI-specific." (PMID 33505428, 2020). "Dextran-stabilized SPIONs targeted with an anti-insulin-like growth-factor binding protein 7 (anti-IGFBP7) single domain antibody were proposed as an MRI contrast for glioblastoma." (PMID 30791358, 2019). "In glioblastoma, IGFBP7 is upregulated and its expression level within the tumor correlates with its histological grade and patient prognosis." (PMID 28134287, 2017). "Glioblastoma-secreted TGFβ also increases expression of insulin-like growth factor-binding protein 7 (IGFBP7) in endothelial cells, promoting angiogenesis." (PMID 27586372, 2017). "In glioblastoma, IGFBP7 was shown to stimulate tumour cell proliferation and angiogenesis of brain endothelial cells." (PMID 25887188, 2015). "IGFBP7 expression is low in glioblastoma, lung cancer, pancreatic cancer and liver cancer, while both increased and decreased expression of IGFBP7 have been reported in breast and prostate cancer." (PMID 24427302, 2014). "Insulin-like growth factor-binding protein 7 (IGFBP7) is an abundant, selective and accessible biomarker of glioblastoma multiforme (GBM) tumour vessels." (PMID 20959824, 2010). "Insights into mechanisms of IGFBP7 expression in the glioblastoma environment have come from in vitro experiments, which demonstrated that TGF-β1 secreted from glioblastoma tumour cells stimulate IGFBP7 production in human brain endothelial cells (HBECs)." (PMID 20959824, 2010). "IGFBP7 mRNA levels were found to be upregulated in lymphoid neoplasm diffuse large B-cell lymphoma, esophageal carcinoma, glioblastoma multiforme, head and neck squamous cell carcinoma, acute myeloid leukemia, brain lower grade glioma, pancreatic adenocarcinoma, stomach adenocarcinoma, and thymoma." (PMID 37304887, 2023). "Pan-cancer analysis based on TCGA data revealed that IGFBP7 was significantly upregulated in GC, esophageal cancer, and pleomorphic glioblastoma, among other cancer tissues, while its expression was downregulated in bladder cancer, renal cell carcinoma, and cervical cancer." (PMID 37568781, 2023). "Other reports claimed that IGFBP7 was also robustly expressed in glioblastoma blood vessels and could induce the formation of “capillary-like tubes” by endothelial cells of the brain." (PMID 32500027, 2020). "Exogenously applied IGFBP7 also reduced proliferation and induced senescence in glioblastoma (GBM) cell lines." (PMID 39045455, 2024). "The anti-IGFBP7 sdAb developed in this study was demonstrated to bind specifically to both human and mouse GBM vessels in brain tissue sections and to tumour vessels after systemic injection in a mouse model of orthotopic glioblastoma." (PMID 20959824, 2010). "In a glioblastoma multiforme (GBM) mice model and in ex vivo human GBM tissue, IRDyeCy5.5-labelled anti-IGFBP7 VHHs did bind to GBM vessels at 10 min to 24 h after injection, but did not to normal brain vessels." (PMID 37746282, 2023). "However, Pen and colleagues reported that IGFBP7 expression is upregulated in ECs and the vascular abluminal basal lamina in glioblastoma multiforme (GBM)." (PMID 37660019, 2023).
glioblastoma (continued). "The biodistribution of anti-IGFBP7 sdAb-PEGylated NPs-Cy5.5 and non-targeted PEGylated NPs-Cy5.5 after systemic injection was examined by in vivo imaging in mice bearing 10-day-old orthotopic glioblastoma tumours." (PMID 20959824, 2010). "Similarly, a nanobody directed against insulin-like growth factor-binding protein 7 (IGFBP7; VHH 4.43), was able to selectively detect glioblastoma (GBM) blood vessels after systemic injection in orthotopic GBM mouse models." (PMID 34439797, 2021).
hepatocellular carcinoma (20 papers, 2010 to 2024). A malignant tumor that arises from hepatocytes. "This peptide is downregulated in hepatocellular carcinoma lesions, compared with its expression in adjacent healthy tissue, and in IGFBP-7-deficient mice, the spontaneous development of liver tumors is observed." (PMID 38541155, 2024). "Numerous studies have confirmed the association between IGFBP7 and various cancers, including hepatocellular carcinoma, breast cancer, esophageal cancer, colorectal cancer, and prostate cancer." (PMID 39081862, 2024). "IGFBP7 expression has been shown to be inversely correlated with tumour grade and stage in hepatocellular carcinoma and lung cancer, and has been associated with favourable outcomes in breast, pancreatic, colorectal and liver cancer patients." (PMID 25886299, 2015). "In breast, colorectal and hepatocellular carcinoma patients down-regulation of IGFBP7 in tumor cells was associated with a worse prognosis." (PMID 26450156, 2015). "Methylation dependent silencing of IGFBP7 was reported as associated with unfavourable outcome in lung-, breast-, and pancreatic cancer, as well as hepatocellular carcinoma." (PMID 25887188, 2015). "An association between low IGFBP7 expression and poor outcome was also observed in pancreatic ductal, breast and hepatocellular adenocarcinoma." (PMID 25886299, 2015). "Finally, IGFBP7 has also been associated with chemosensitivity, as a lower expression was noted in hepatocellular cancer cells resistant to interferon and NSCLC cells resistant to cisplatin compared to the parental cells." (PMID 38999963, 2024). "On the other hand, elevated levels of tissue expression of IGF2, IGF1R or other IGF system components (IGFBP7), may indicate an increased risk of hepatocellular carcinoma." (PMID 29702590, 2018). "Downregulated expression of IGFBP7 was reported in liver carcinomas, lung cancer and prostate cancer." (PMID 38893148, 2024). "Deletion of IGFBP7 presents a pro-inflammatory and immunosuppressive microenvironment and promotes the development of hepatocellular carcinoma." (PMID 37088808, 2023). "Low expression of tumor suppressor IGFBP7 was responsible for angiogenesis in hepatocellular carcinoma." (PMID 30970615, 2019). "In hepatocellular carcinoma and malignant melanoma IGFBP7 was even suggested as therapeutic agent as it inhibited tumor cell viability and promoted apoptosis in vivo and in vitro." (PMID 26450156, 2015). "Utilizing detection techniques such as qRT-PCR, immunohistochemistry, Northern blot, and Western blot, studies have revealed that IGFBP7 expression is generally downregulated in hepatocellular carcinoma, melanoma, and lung cancer, while showing an upregulation trend in esophageal cancer." (PMID 39081862, 2024). "One limitation of our study is that we observed only mild-to-moderate fibrosis; further studies in severer stages of fibrosis, cirrhosis, and hepatocellular carcinoma derived from NAFLD are needed in order to establish a complete association between fibrosis, IGFBP-7, and senescence during NAFLD." (PMID 38541155, 2024). "Moreover, deletion of IGFBP7 was found to increase proliferation in hepatocellular carcinoma by a constitutively active IGF signaling." (PMID 32511227, 2020). "Moreover, adenovirus expressing IGFBP7 has proof it anti-metastasis effect on Hepatocellular carcinoma by xenograft models." (PMID 25880247, 2015). "IGFBP7 activity has not yet been reported in sarcoma, but has been associated with e. g. hepatocellular carcinoma." (PMID 23688189, 2013). "IGFBP7 expression was significantly downregulated in human hepatocellular carcinoma (HCC) tissue samples and cell lines as compared with normal liver and hepatocytes, respectively." (PMID 39045455, 2024).
lung carcinoma (19 papers, 2013 to 2025). "Another gene that displayed higher expression in the younger/immature matrix fibroblasts was IGFBP7, which has previously been associated with resistance to lung cancer by performing tumor suppression function, especially in epithelial cells." (PMID 38540357, 2024). "IGFBP7 expression is highly associated with EGFR-TKI resistance in lung cancer cells." (PMID 30609749, 2019). "Preclinical research suggests that IGFBP-7 promotes acquired resistance to osimertinib in lung cancer." (PMID 40199609, 2025). "Another recent study demonstrated that enhanced IGFBP-7 expression promoted resistance to epidermal growth factor receptor tyrosine kinase inhibitors in lung cancer cells by mediating the IGF-1R pathway." (PMID 36902237, 2023). "In early-stage lung cancer nodules and metastatic lung cancer, IGFBP7+PLVAP+ tumor ECs were greatly amplified, whereas the proportion of extra-alveolar capillary ECs (cECs), EDN1+CCL2+ ECs, decreased." (PMID 37187731, 2023). "Another report suggested that downregulation of IGFBP7 rendered lung cancer cells resistant to cisplatin and altered the sensitivity to cisplatin-based anticancer therapy." (PMID 32500027, 2020). "IGFBP‐7 has been found to act as a tumor suppressor in lung cancer with its expression being high in healthy lung tissue but downregulated in lung cancer largely due to DNA hypermethylation." (PMID 32592613, 2020). "DNA hypermethylation resulted in lower IGFBP7 expression for both lung cancer cell lines and primary lung tumors." (PMID 32500027, 2020). "While enhanced IGFBP7 expression promoted resistance to EGFR-TKIs in lung cancer cells, IGF-1R activation has been reported to confer acquired resistance to EGFR-TKIs." (PMID 30609749, 2019). "Overexpression of IGFBP7 in lung cancer cells inhibits anchorage-independent growth and xenograft tumor growth." (PMID 31183073, 2019). "Our findings suggest that co-targeting of EGFR and IGFBP7 is an effective strategy for treating EGFR-mutant lung cancer." (PMID 30609749, 2019). "The IGFBP7 gene is aberrantly methylated in various tumors, and methylation was previously detected in 46 out of 90 lung cancers examined by MSP." (PMID 23381221, 2013). "The overall concordances between gene expression ratios and methylation levels of SLIT2, MAL and IGFBP7 were 67, 89 and 78% in lung cancer cell lines." (PMID 23381221, 2013). "Among them, IGFBP-7 seem to have such a behavior in lung cancer." (PMID 36902237, 2023). "Among them, IGFBP2, IGFBP3, IGFBP4, IGFBP6 and IGFBP7 showed higher expression levels, especially in gastric, liver and lung cancer cell lines; conversely, IGFBP1, IGFBP5 and IGFBPL1 showed relatively lower expression, particularly in colorectal, gastric and kidney cancer cell lines." (PMID 37088808, 2023). "Hence, the role of IGFBP-7 in lung cancer is somewhat controversial and requires further investigation." (PMID 36902237, 2023). "IGFBP7 was particularly evident in the small airway bronchial epithelial cells and the cytoplasm of lung bronchial epithelial cells, despite low expression of IGFBP7 in primary lung cancer tissues." (PMID 32500027, 2020). "The expression of IGFBP7 in lung cancer tissues is lower than that in normal tissues, so IGFBP7 may be a tumor suppressor gene, inhibiting tumor growth by promoting cell apoptosis and senescence and inhibiting the invasion and migration of cancer cells." (PMID 32832569, 2020). "A high serum level of IGFBP7 was correlated with a positive lymph node status in lung cancer." (PMID 30609749, 2019).